PSMB8 (proteasome 20S subunit beta 8)
Diseases named in the same sentence as PSMB8 in open-access papers (continued):
Sharing a sentence is not in itself a finding about the gene and the disease.
osteosarcoma (1 paper, 2023). A usually aggressive malignant bone-forming mesenchymal neoplasm, predominantly affecting adolescents and young adults. "Furthermore, 49 (10.6%) tumors had LOH affecting APP gene(s) in the HLA region (TAP1/2, TAPBP, PSMB8/9, HSPA1A-L), including 14 (20.6%) osteosarcoma and five (22.7%) GBM cases with LOH in both TAP1 and TAP2." (PMID 38318504, 2023).
pancreatic adenocarcinoma (1 paper, 2021). "The analysis of differentially expressed PSMB8 in TCGA revealed significant differences except for kidney chromophobe (KICH), pancreatic adenocarcinoma (PAAD), and prostate adenocarcinoma (PRAD)." (PMID 34650125, 2021).
primary immunodeficiencies (1 paper, 2025). "This is supported by the fact that among the 38 interferon response genes (category II), only OAS1, ADAR, PSMB8, SAMHD1 and the IRF transcription factors have been implicated in causing primary immunodeficiencies." (PMID 41038828, 2025).
schizophrenia (1 paper, 2025). A major psychotic disorder characterized by abnormalities in the perception or expression of reality. "The microglial H-MAGMA-risk genes BAG6, NEU1, PRRC2A, PSMB8, PSMB8-AS1 and PSMB9 were associated with MS, ALS and schizophrenia." (PMID 40202986, 2025).
scrapie (1 paper, 2014). A fatal disease of the nervous system in sheep and goats, characterized by pruritus, debility, and locomotor incoordination. "The downregulation of PSMA7 and UCHL1 genes and the positive association of PrPSc deposition with PSMB8 expression in both preclinical and clinical stages of natural scrapie in the LRS of sheep is in line with the impaired proteasome function described in prion diseases of the nervous system." (PMID 24450868, 2014).
squamous cell carcinoma (1 paper, 2025). A carcinoma arising from squamous epithelial cells. "Notably, thymic carcinomas differed from squamous cell carcinomas in other organs by higher levels of β5i (PSMB8) and constitutive proteasome β5 (PSMB5)." (PMID 41339338, 2025). "Furthermore, we were able to show that TC are distinguished from histologically similar squamous cell carcinomas in other organs (e.g., lung and head and neck) by their increased expression of the immunoproteasome β5i (PSMB8) subunit together with high levels of the CPS subunit β5 (PSMB5)." (PMID 41339338, 2025).
urothelial bladder carcinoma (1 paper, 2023). "Because recent evidence has demonstrated an immunological role for proteasomes in various malignancies, including urothelial bladder carcinoma (UBC), we evaluated single nucleotide polymorphisms (SNPs) in PSMB9 and PSMB8." (PMID 36937130, 2023).
urothelial carcinoma (1 paper, 2022). A malignant neoplasm derived from the transitional epithelium of the urinary tract (urinary bladder, ureter, urethra, or renal pelvis). "Our previous studies found a co-expression network associated with CD8+ T lymphocyte invasion in urothelial carcinoma, which contains PSMB8, PSMB9, PSMB10, PSME2, IRF1 and other genes." (PMID 36700205, 2022).
tumor (88 papers, 2003 to 2026). "In gastric cancer, the high nuclear expression level of PSMB8 has been linked to the depth of tumor invasion, lymph node metastasis, and an unfavorable prognosis." (PMID 40335825, 2025). "Along these lines, tumors with high expression of LMP-7 (encoded by PSMB8) were shown to have more tumor-infiltrating lymphocytes in each BC subtype." (PMID 39796785, 2025). "This suggests that it has robust anti-tumor activity and has potential to be used as a treatment for cancers where high levels of PSMB8 are associated with poor overall survival." (PMID 41228214, 2025). "When looking at the OS and metastases, significant associations were found for PSMB8-expressing tumor cells and OS, as well as PSMB9-expressing tumor cells and brain metastasis." (PMID 36746983, 2023). "The association of aberrant expression of PSMB8 have been asynchronous with regard to tumor prognosis." (PMID 34650125, 2021). "PSMB8-deficient mice were found to be resistant to chronic inflammation and neoplasia, with reduced expression of chemokines CXCL-1, CXCL-2, and CXCL-3." (PMID 34944095, 2021). "Moreover, with carfilzomib having robust anti-tumor activity, it has potential as a treatment option for cancers where high levels of PSMB8 are associated with poor overall survival." (PMID 41228214, 2025). "PSMB8 is associated with several cancers as both a tumor promoter and suppressor." (PMID 37974228, 2023). "In our study, overexpression of PSMB8 mRNA and higher levels of proteins encoded by PSMB8 were found in ccRCC tissues compared to normal tissues, and was significantly related with patients' individual cancer stages and tumor grades." (PMID 35693739, 2022). "Likewise, increased PSMB8 expression in TNBC tumor samples was associated with better disease-free outcomes, including in those with metastatic disease." (PMID 34944095, 2021). "Similarly, microarray profiling of gastric adenocarcinoma samples revealed that PSMB8 expression in tumor tissue was associated with poor prognosis." (PMID 34944095, 2021). "Polymorphisms in genes encoding the iP subunits β1i (PSBM9) and β5i (PSMB8) have been associated with an increased risk of tumor development, including the development of esophageal carcinoma, cervical carcinoma, oral squamous cell carcinoma, prostate cancer, and colon cancer." (PMID 34206607, 2021). "Notably, specific markers of dendrite cells exhibited the tightest association with PSMB8 expression in terms of tumor-related immune infiltration patterns." (PMID 34650125, 2021). "Besides, given that PSMB8’s strong associations with immune checkpoints and immune cells, it may serve as a promising biomarker to assess the immune activity of tumor microenvironment and predict immunotherapy response." (PMID 40334200, 2025). "Finally, the polytrophic function of PSMB8 may represent an initial effect, and the underlying mechanisms engaged in tumor activities remain still elusive." (PMID 34650125, 2021). "In this study, we analysed gene chip data from Lingonberry extract-treated HepG2 tumour-bearing mice using bioinformatics tools, employing a cross-species, multi-level screening strategy to identify PSMB8 as the core regulatory gene." (PMID 41899474, 2026). "Another compound targeting PSMB8 is M3258, which was shown to efficiently induce the apoptosis of tumor cells in multiple myeloma xenograft models and presenting a favorable safety profile." (PMID 40698074, 2025). "Subsequently, we sought to delve deeper into the potential connections between PSMB8, the tumor immune microenvironment, and immune-related genes." (PMID 40334200, 2025). "We observed a significant differential expression of PSMB8 between tumor and normal samples across 16 cancer types." (PMID 40334200, 2025). "PSMB8 protein expression profiles in patients of different subtypes showed that PSMB8 was more highly expressed in tumor tissues." (PMID 40335825, 2025).
tumor (continued). "The results indicated a consistent decrease in BCL2 and BMP5 expression in most tumor samples, while PSMB8 and PSME2 showed increased expression." (PMID 41403941, 2025). "Depletion of PSMB8 or TMZ combination inhibited GBM tumor growth by reducing the downstream protein expression and SMAD2 phosphorylation of the TGF-β pathway." (PMID 40335825, 2025). "The western blotting and IHC analysis results showed that the protein expression of PSMB8 was significantly higher in ATC tumor tissues than in non-tumor adjacent tissues." (PMID 37974228, 2023). "Psmb8 knockout was sufficient to rescue the FAK-/- tumour growth delay, suggesting that Psmb8 upregulation was critical in restraining FAK-/- tumour growth." (PMID 36977556, 2023). "The PD-1 expression scores of tumour cells and immune cells in patients with high expression levels of PSMB8, PSMB9, and PSMB10 were greater than low expression samples." (PMID 36700205, 2022). "This was supported by a mouse model, which demonstrated that PSMB8 inhibition decreased tumor vessel formation." (PMID 34944095, 2021). "We determined that the expression of PSMB8 was positively correlated with the number of neoantigens only in SKCM tumor tissues (R = 0.241, P < 0.05)." (PMID 34650125, 2021). "The results indicated that compared with the control (si-NC), the silence of PTPN6 and PSMB8 significantly suppressed cell growth (p < 0.05), and the formation of tumor cell colonies (p < 0.01)." (PMID 35127714, 2021). "It has been observed that PSMB8−/− mice implanted with B16 tumors have significant tumor growth and disease development." (PMID 34944095, 2021). "The authors further attributed the pro-tumor effects of PSMB8 to reduced secretion of IL-17A in inflamed colons of PSMB8 deficient mice." (PMID 34944095, 2021). "In detail, we first compared the expression of PSMB8 in normal tissues, tumor cell lines, and pan-cancer." (PMID 34650125, 2021). "Further, to distinguish between the two potential roles of PSMB8, we conducted a pan-cancer expression profile analysis using datasets from TCGA and the GTEx databases to compare differences in expression between tumor and normal tissue." (PMID 34650125, 2021). "These seven cancer types identified a subset in which the TME was irrelevant to PSMB8 expression, and thus the predictive role of PSMB8 was far from optimal in this subgroup, which is frequently encountered in the search for tumor biomarkers." (PMID 34650125, 2021). "The ambiguous role for PSMB8 in oncogenesis and disease progression seems to hinge on the fact that high levels of immunoproteasome expression can facilitate or impede tumor development in different contexts." (PMID 34944095, 2021). "Using GTEx and TCGA, we found that PSMB8 expression was generally lower in normal tissues, while exhibited varied expression in tumor cell lines of CCLE." (PMID 34650125, 2021). "Elevated nuclear expression of PSMB8 was related to lymphovascular tumor emboli, increased tumor size, and perineural invasion of tumor cells." (PMID 26894977, 2016). "High PSMB8 levels also correlate with more active immune pathways, a greater presence of antitumor immune cells, fewer protumor immune cells, and higher immunoscores, underscoring its significant role in tumor immunology." (PMID 40334200, 2025). "However, overexpression of PSMB8 increased cytotoxicity and apoptosis, and promoted radiation-induced tumor necrosis in rectal cancer." (PMID 40335825, 2025). "Indeed, PSMB8- and 10-deficient cells exhibited decreased activation of IRFs, STATs and NF-κB, which in turn prevented the expression of multiple-pro-inflammatory genes, which may impair the recruitment, activation and polarization of adaptive immune cells with anti-tumor activity within the TME." (PMID 40698074, 2025). "Earlier research has indicated that PSMB8 exhibits high expression levels in tumor tissues." (PMID 40335825, 2025).
tumor (continued). "Interestingly, the 3 main immunoproteasome genes, PSMB8, PSMB9, and PSMB10, which digest cellular protein to antigenic peptides for antigen presentation, were also upregulated by VC in the WT tumor cells, as indicated by PSMB8 and others." (PMID 39388288, 2024). "To better understand how FAK and Psmb8 might act to restrain tumour growth, we next profiled the antigen repertoire using mass spectrometry (MS)-based immunopeptidomics." (PMID 36977556, 2023). "Tumor cells demonstrated enriched expression of the proteasome and immunoproteasome subunits Psmb8 and Psmb9 and major histocompatibility complex class I (MHC I) genes H2-K1, H2-D1, and B2m, consistent with upregulation of antigen processing and presentation machinery." (PMID 37041154, 2023). "PSMB8 could be detected with a relatively high expression in various immune cells and tumor cells, and PLAAT4 showed a relatively high expression in CD4+ T cells, CD8+ T cells, NK cells, and proliferative T cells." (PMID 36072600, 2022). "Thus, in conclusion, we found the upregulated expression of KNTC1 and PSMB8 in tumor tissues of NSCLC." (PMID 35933405, 2022). "Both KNTC1 and PSMB8 could act as tumor promotor in the development and progression of NSCLC through promoting cell proliferation, colony formation, cell migration and suppressing cell apoptosis." (PMID 35933405, 2022). "Besides, how PSMB8 interacts with immune cell infiltration in the tumor microenvironment requires further research." (PMID 34650125, 2021). "In the field of TC research, experimental data from multiple cell types have confirmed that miR-451a could suppress tumour cell proliferation and invasion by targeting PSMB8 and ZEB1." (PMID 34595349, 2021). "Thus, only PSMB8 expression in LUSC was inconsistent and finally drew a conclusion that overexpression of PSMB8 appeared more frequently in the tumor tissues than in their normal counterparts." (PMID 34650125, 2021). "Next, we explored differences in expression between tumor and normal tissues using TCGA datasets and determined that PSMB8 was generally prone to be over-expressed in the most tumor tissues compared to normal tissues, except for LUSC, PAAD, PRAD, and KICH tumors." (PMID 34650125, 2021). "PSMB8 and PSMB9 overexpression was found to highly associate with CD4+ and CD8+ T-cell infiltration, regulatory T-cells, NK cells and M1-macrophages, in agreement with a role for IP subunit overexpression in enhancing the immune response in the tumor." (PMID 32060274, 2020). "However, the detailed oncogenic mechanisms of PSMB8 and its interactions with tumor immunology and non-coding RNAs remain unclear." (PMID 40334200, 2025). "Moreover, PARP9 expression positively correlates with metastasis of axillary lymph node and is negatively associated with ER expression, as well as PSMB8 and PSMB9 and immunoproteasomes, which induce tumor angiogenesis via VEGF-A and are overexpressed in most cancers, including BC." (PMID 36766731, 2023). "It is also possible that Psmb8 incorporation into the proteasome could result in presentation of an antigen repertoire more likely to mediate a successful encounter between T-cells and tumour cells." (PMID 36977556, 2023). "Therefore, the TCGA database was initially utilised to investigate the impact of PSMB8 core subunit and regulatory subunit constituent genes on the tumour microenvironment of solid tumours and whether they may be utilised as predictors of clinical survival." (PMID 36700205, 2022). "In the present study, similar to PSMB8, up-regulated PSMB9 transcriptional levels and higher PSMB9 encoding protein levels were found in ccRCC tissues compared to normal tissues, and PSMB9 mRNA expression was significantly related with patients' individual cancer stages and tumor grades." (PMID 35693739, 2022). "PSMB8 affects neuroinflammation by regulating the activity of immunoproteasome, while COL17A1 and BICC1 promote the progression of PNI in tumor cells by regulating matrix homeostasis and ECM." (PMID 41132793, 2025).
tumor (continued). "In line with this, RT-qPCR analysis demonstrated that knockdown of PSMB8 or TMZ treatment dramatically reduced the expression of c-Myc and cyclin D1 (tumor growth markers) and enhanced caspase- 3 (tumor apoptosis marker)." (PMID 40335825, 2025). "In this study, we discovered that PSMB8 had a similar molecular profile to HOXD9 in ATC and they were both upregulated in tumor tissue." (PMID 37974228, 2023). "As expected, the benefits of higher PSMB8- and PSMB9-positive tumor cells content were augmented when considering high-grade cancers only." (PMID 36746983, 2023). "The IFN-gamma inducible genes (PSMB8/β5i, PSMB9/β1i, PSMB10/β2i), together with their chaperones have command of the tumor vulnerability to antigen-dependent killer cells." (PMID 34650125, 2021). "An experimental study determined that down-regulated incorporation of PSMB8 into immunoproteasome could attenuate its formation, laying the foundation of the key part of PSMB8 in the proteolytic activity and protein homeostasis in maintenance of tumor development." (PMID 34650125, 2021). "PSMB8, PSMB9, PSMB10, PSME2, TAP1, and IRF1 promote CD8+ T cell infiltration by enhancing MHC class I tumor antigen processing." (PMID 33330025, 2020). "Here, the expression of IP subunit PSMB8 correlated with RARRES3 in BM-MSC and four tumor datasets, and also correlated with HLA-C in all but one of these cancer types." (PMID 28051153, 2017). "Immunoproteasome genes are known to be mainly expressed by immune cells, meaning that expression of PSMB8 and PSMB9 genes in tumor samples could be driven by infiltrating immune cells." (PMID 39796785, 2025). "Mechanically speaking, the immunoproteasome subunit PSMB8 was involved in the processing of endogenous proteins into peptides that were presented via MHC I to CD8+ T cells, a critical step in activating anti-tumor immunity." (PMID 40334200, 2025). "Our data show a clear correlation between high ImP expression and better outcomes, most notably for TNBC patients and when tumor cells rather than stromal or immune cells express PSMB8 or PSMB9." (PMID 36746983, 2023). "Psmb9 depletion did not rescue FAK-/- tumour growth, implying that an intermediate proteasome containing Psmb8 is sufficient to restrain FAK-/- tumour growth." (PMID 36977556, 2023). "As such, some tumors contained high amounts of PSMB8+ CK8-18+ (tumor) cells, while some others were completely negative and the same phenotypes were observed for PSMB9." (PMID 36746983, 2023). "PSMB8 expression in tumor cells not just reprograms the cellular pathways within the cell but also affects the tumor microenvironment." (PMID 34944095, 2021). "Eight co-expressed genes (PSMB8, PSMB9, PSMB10, PSME2, TAP1, IRF1, FBOX6, ETV7) were identified as CD8+ T cell-related genes that promoted infiltration of CD8+ T cells, and were enriched in the MHC class I tumor antigen presentation process." (PMID 33330025, 2020). "Presence of somatic variants in genes related to antigen presentation, including HLA-A, HLA-B, HLA-C, B2M (β-2-microglobulin), TAP2, and PSMB8 (LMP-7), did not predict tumor classification." (PMID 30824826, 2019). "The metastatic propensity signature (high COL17A1/PSMB8, low CTRC) suggests: PNI facilitation via collagen remodeling (COL17A1), immune-evasion priming through proteasomal antigen processing (PSMB8),protective trypsin depletion in tumor microenvironment (CTRC)." (PMID 41132793, 2025). "In some studies, the expression level of Proteasome Subunit beta 8 (PSMB8), Lipocalin 2 (LCN2), T Cell Immunoreceptor with Ig and ITIM Domains (TIGIT), High Mobility Group Box (HMGBs) proteins, and others were found to be greater in tumor tissue as compared to normal tissue." (PMID 38730579, 2024). "However, we found a strong correlation between the numbers of PSMB8 + and PSMB9 + cells, as well as between PSMB8 + and PSMB9 + tumor cells, which would suggest that using only one or the other could potentially be sufficient." (PMID 36746983, 2023).